CCNQ (cyclin Q)
Description:
Activating cyclin for the cyclin-associated kinase CDK10.
Synonyms: FAM58A; CycM
Tractability: No criterion of Open Targets' tractability assessment is met for any kind of drug.
Gene: Protein-coding gene on chromosome X (153,587,925 to 153,600,045, reverse strand). Ensembl gene ENSG00000262919.
Subcellular location (Human Protein Atlas): Cytosol; Nucleoplasm
Gene Ontology:
Molecular function: protein binding; cyclin-dependent protein serine/threonine kinase regulator activity
Biological process: regulation of cell cycle G2/M phase transition; regulation of transcription by RNA polymerase II
Cellular component: cyclin-dependent protein kinase holoenzyme complex
Gene-disease validity (ClinGen):
ClinGen rates the evidence that CCNQ causes each of these diseases.
syndactyly-telecanthus-anogenital and renal malformations syndrome (X-linked): Moderate. This syndrome is characterized by the association of toe syndactyly, facial dysmorphism including telecanthus (abnormal distance between the eyes) and a broad nasal tip, urogenital malformations and anal atresia.
Homologues: Orthologues: chimpanzee FAM58A (100% identical), macaque CCNQ (91% identical), mouse Ccnq (89% identical), guinea pig CCNQ (88% identical), pig CCNQ (88% identical), rat Ccnq (77% identical), rabbit CCNQ (76% identical), dog CCNQ (72% identical), tropical clawed frog ccnq (69% identical), zebrafish ccnq (58% identical), Drosophila melanogaster koko (34% identical), Caenorhabditis elegans cit-1.1 (19% identical), and 1 more. Paralogues in human: CCNL2 (30% identical), CCNL1 (29% identical), CCNK (23% identical), CCNT2 (22% identical), CCNT1 (21% identical), CCNH (17% identical).
Diseases named in the same sentence as CCNQ in open-access papers:
CCNQ is named in the same sentence as 5 diseases in open-access papers, as found by Europe PMC text mining. Sharing a sentence is not in itself a finding about the gene and the disease. The quoted sentences say what the papers report.
STAR syndrome (6 papers, 2014 to 2025). "STAR syndrome is caused by pathogenic variants in Cyclin Q (CCNQ)." (PMID 39800774, 2025).
CCNQ also shares sentences with these, for which no sentence is quoted: cancer (3 papers); tumor (2); colon cancers (1); glioblastoma (1).